TNF (tumor necrosis factor)
Diseases named in the same sentence as TNF in open-access papers (continued):
Sharing a sentence is not in itself a finding about the gene and the disease.
Stroke (continued). "For example, in stroke models, increased lipid droplet accumulation in microglia influences pro-inflammatory phenotypic changes, leading to elevated secretion of factors like TNF-α, IL-6, and IL-1, which exacerbate neuroinflammation." (PMID 40182755, 2025). "In our study, the up-regulation of TNFα was determined on the 7th day post-stroke, which may indicate a relationship between the inflammatory reaction and intense vascular remodeling one week after ischemia in pigs." (PMID 40332314, 2025). "In stroke patients, the rise in TNF-α can be measured 6–12 h from symptom onset." (PMID 40362186, 2025). "Furthermore, the gene expression of TNFα was significantly elevated in the ipsilateral hemisphere at both 6 h and 7 days post-stroke induction when compared to in the contralateral hemisphere (p < 0.05)." (PMID 40332314, 2025). "IL-6, along with other inflammatory cytokines such as TNF-α and IL-1β, may play an important role in cognitive impairments following a stroke, as they are key regulators of the acute phase response to inflammation and tissue damage." (PMID 40305179, 2025). "After a stroke, microglia preferentially respond to pathological stimuli and secrete IL-1α, TNF-α, and C1q after activation, triggering reactive signals of astrocytes through soluble and membrane-bound signaling molecules, inducing their transformation into pro-inflammatory astrocytes." (PMID 40289984, 2025). "Soluble tumor necrosis factor-α (TNF-α) receptors secreted by adipose tissue may neutralize the biological impact of TNF-α, and contrast the post-stroke pro-inflammatory state." (PMID 38440787, 2024). "In our experiment, the post-surgical assessment of proinflammatory cytokines, including IL-1β, IL-6, and TNF-α in the hippocampal tissue, revealed that the inflammatory response in the CNS of mice with stroke was markedly higher than that in mice undergoing sham operations." (PMID 39758888, 2024). "In addition, plasma H19 levels were positively correlated with tumor necrosis factor-α (TNF-α) levels and National Institutes of Health Stroke Scale scores." (PMID 39021183, 2024). "In addition to the anti-inflammatory roles of IL-10 in the inflammatory response after stroke, IL-10 is also a negative regulator of pro-inflammatory cytokines TNF-α, IL-1β and IL-6." (PMID 38421829, 2024). "When stroke occurs, the NF-κB inflammatory signaling pathway is activated to stimulate the phosphorylation of P65 protein to p-P65, and then p-P65 enters the nucleus to further induce the release of inflammatory factors including TNF-α, IL-1β and IL-6 etc.." (PMID 38756375, 2024). "In a murine study, they utilized a 90-min HBOT treatment at 2.5 absolute atmospheres before inducing injury with either tumor necrosis factor-alpha (TNF-α) or lipopolysaccharide (LPS) to simulate inflammation-related secondary cell death, common in stroke and TBI." (PMID 39445195, 2024). "It has been shown that P2Y1R-ANT suppresses microglial activation but fails to improve functional recovery after traumatic brain injury, whereas the stimulation of P2Y1R on microglia suppresses TNF-α production and exerts neuroprotection in the early stage of stroke." (PMID 37676390, 2024). "In conclusion, these findings provide the first evidence that estradiol inhibits TNF-α-induced PC migration by specifically downregulating miR638 via ER-β and may protect the neurovascular unit during injury/stroke via this mechanism." (PMID 39518968, 2024). "This is the first time that the microglial glycolysis is linked to TNF and CCL in stroke." (PMID 39021802, 2024). "Although the analyses were performed on the association of FFA with TNF-α, HOMA2S, HOMA2B, HbA1c, dyslipidemia, hypertension, coronary heart disease, stroke, and chronic kidney disease, we found that adiponectin only mediated the association between FFA and TNF-α." (PMID 38886355, 2024).
Stroke (continued). "Additionally, the inflammatory response following a stroke triggers the release of cytokines, including tumor necrosis factor-α (TNF-α), interleukins (ILs), and interferon-γ (IFN-γ)." (PMID 39519182, 2024). "Interleukins such as IL-1β, TNF-α, and IL-6 can help mitigate the inflammatory response and improve outcomes in stroke patients, which could be another immunomodulation target." (PMID 39633897, 2024). "TNF-α, IL-6, IL-1β, and IL-10 were also measured in peripheral blood samples to examine the possible effect of peripheral inflammatory response on the recurrent stroke." (PMID 38216560, 2024). "Variations in genes such as IL-6 and TNF-α may affect inflammatory responses and stroke development." (PMID 39655053, 2024). "Although TNF-α and NF-κB have pleiotropic roles, our data indicated that suppression of NF-κB together with these inflammatory pathways could be promising for stroke recovery." (PMID 37676390, 2024). "Interestingly, stroke mice with HFD showed a significant upregulation of plasma TNF-α, IL-6 and MCP-1 amounts compared to sham controls within 3 h after stroke onset." (PMID 39845972, 2024). "In both types of stroke, there is a robust inflammatory reaction characterized by neutrophil and macrophage activation, along with the release of inflammatory mediators like tumor necrosis factor-α (TNF-α), interleukin-6 (IL-6), and C-reactive protein (CRP)." (PMID 39329013, 2024). "Notably, at earlier time points within 24 h post-stroke, microglial M1 polarization is significantly enhanced, accompanied by elevated levels of pro-inflammatory cytokines like TNF-α, IL-1β, IL-6, and chemokines C-C motif chemokine ligand 2/3 (CCL2/3)." (PMID 39633709, 2024). "TNF signaling pathways may play a significant role in the treatment of stroke and traumatic brain injury." (PMID 38783945, 2024). "Hallmark pathway analysis revealed that some upregulated pathways, such as TNFα signaling via NF-κB, hypoxia, and apoptosis, were shared between the pericytes subclusters from the ipsilateral area at 1 h and subcluster 5 at 12 and 24 h after stroke." (PMID 37378751, 2024). "Moreover, serum IL-6 and TNF-α are abnormally elevated among stroke patients (< 24 h), and IL-6 level is positive correlation with stroke severity and poor outcomes." (PMID 38879549, 2024). "Once a stroke occurs, astrocytes and microglia as the first line of immune defense are activated, induce cytokines, including interleukin (IL), tumor necrosis factor (TNF), and interferon." (PMID 39763672, 2024). "After a stroke, the expression of TNF-α, IL-1β, and IL-6 increased, aggravating the brain injury." (PMID 38756772, 2024). "Furthermore, we observed noteworthy disparities in the plasma levels of IL-2, IL-4, IL-6, IL-10, TNF-α, and INF-γ between patients devoid of risk factors and those presenting with comorbid risk factors associated with stroke." (PMID 38287458, 2024). "Collectively, these results suggest that the decrease in tight junction protein expression in gut epithelial cells following stroke may be mediated by the proinflammatory cytokine TNF-α and NF-kb pathway in ischemic stroke." (PMID 36781906, 2023). "In the hours following stroke, the pro-inflammatory response peaks at 6 h where both microglia and astrocytes are activated, producing cytokines such as interleukin 1 beta (IL-1β) and tumor necrosis factor alpha (TNF-α)." (PMID 36831312, 2023). "In the early stage post-stroke, M1 phenotype microglia are considered to cause damage to the surrounding neuronal cells by secreting pro-inflammatory factors (including IL-6, IL-1β, IFN-γ, TNF-α, IL-15, IL-18, and IL-23)." (PMID 37464832, 2023). "Our analysis corroborates the evidence for its role in the natural history of stroke-related health deterioration, given that many members of the senescence-associated secretory phenotype (SASP; here: SERPINE1, IL6, CRP, TNF and TGFB1) are placed center stage in the interaction network." (PMID 35953740, 2023).
Stroke (continued). "In addition, our previous study found that inhibition of LMP2 decreased the protein levels of IL-1β and TNF-α in rat stroke model." (PMID 36978132, 2023). "While increased intra-lesional TNF appears to be beneficial in the acute stroke stage, permanently elevated TNF serum levels may indicate ongoing neuroinflammation driving continued cell death following stroke." (PMID 35953740, 2023). "Additionally, direct comparisons between CIRP and established biomarkers, such as C-reactive protein, IL-6, and TNF-α, should be conducted to assess their predictive value, sensitivity, and specificity for stroke outcomes." (PMID 37521290, 2023). "In addition, recent animal studies and clinical studies have shown an increase in TNF-α levels in peripheral blood after stroke; further, in vitro cellular assays have shown that exogenous TNF-α induces a decrease in eosinophil numbers." (PMID 38066457, 2023). "In addition to IL-1β and TNF-α, IL-6 is also a pleiotropic cytokine that is involved in stroke, but its function is still controversial." (PMID 37951917, 2023). "EE also inhibited the expression levels of inflammatory cytokines including TNFα, IL-6, and IL-1β, which might facilitate functional recovery after stroke." (PMID 36819784, 2023). "While TNF-α inhibition may be beneficial on stroke size and neuromotor deficit at short-term ischemia/reperfusion injury, such a protective effect seems lost when looking at long-term outcome, such as post-stroke neuronal plasticity." (PMID 36745280, 2023). "Considering that inflammatory processes stimulate neuroprotective effects if they persist for a short time but cause neurodegenerative processes if they persist for a longer time, we also examined the time course of TNFα expression in neurons located in the peri-stroke tissue." (PMID 37298395, 2023). "Therefore, cytokines—particularly TNF, IL-1, and IL-6—have attracted considerable interest as potential markers for stroke severity and neurological outcome." (PMID 38102677, 2023). "The confirmation of the harmful effect of CCL5 in the acute phase of stroke is supported by the correlation observed between the biomarkers of inflammation, IL-6 and TNF-α, previously determined by our research centre, which is among the first to be released during ischemia in AIS." (PMID 37759440, 2023). "Due to its complex and multifaceted role in the CNS, TNF may be a potential marker for stroke and brain injury." (PMID 37759909, 2023). "Of the blood markers identified here as being relevant for the long-term outcome after stroke, arguably the most important molecular key players are tumor necrosis factor alpha (TNF), interleukin 6 (IL6), fibrinogen (FGA), and plasminogen activator inhibitor-1 (SERPINE1)." (PMID 35953740, 2023). "Therefore, the effects of other selective TNF alpha inhibitors on post-stroke pain, and a side-by-side comparison with the effects of etanercept, were not included in this review." (PMID 37065345, 2023). "In the acute phase of stroke, activated microglia might deteriorate the outcome through releasing pro-inflammatory factors, such as tumor necrosis factor-α (TNF-α), interleukin-1β (IL-1β), IL-6, and interferon-γ (IFN-γ)." (PMID 36836502, 2023). "In addition, the TNF-alpha levels are increased in the cerebrospinal fluid and serum of stroke cases." (PMID 37240845, 2023). "Neuroinflammation activated by TNF alpha is commonly seen in the sequelae following strokes." (PMID 37065345, 2023). "After stroke, activated microglia induce A1 astrocytes by secreting IL-1α, TNFα, and C1q." (PMID 37464832, 2023). "In addition, optimizing the anti-TNF alpha therapy regimen based on stroke severity and symptoms, patient characteristics, and timing of treatment should be further researched." (PMID 37065345, 2023). "Therefore, the aim of this study is to assess the predictive value of combining iFABP, IL-6, and TNF-α testing for the onset of PSD in hospitalized stroke patients." (PMID 38084247, 2023).
Stroke (continued). "Increased TNF levels have also been confirmed in one human stroke study." (PMID 36636739, 2022). "Similarly, high systemic levels of such pro‐inflammatory cytokines (IL‐6, TNF‐α and IL‐1β) have been directly related to cytokine‐induced sickness behavior after experimental stroke." (PMID 35971650, 2022). "Also, others report elevated TNF-α levels, although with different peak times and contradictory results concerning the correlation between peripheral TNF-α levels and stroke severity." (PMID 36142524, 2022). "Additionally, anti-TNFα treatments, such as administration of infliximab, alleviate endothelial necroptosis and improve outcomes of stroke, suggesting a promising therapeutic modality." (PMID 36186129, 2022). "We have shown that serum IL-6 concentration above 4 pg/mL and TNF-α > 37 pg/mL, determined on the 7th day after stroke, may indicate a high probability of death in patients." (PMID 36142524, 2022). "In addition to the role of TNF-α in stroke, anti-TNF-α-based antistroke therapies have received increasing attention from the researchers." (PMID 35265224, 2022). "Furthermore, treatment with isorhamnetin in stroke mice improved the integrity of the blood-brain barrier and reduced the levels of IL-1β, IL-6, and TNF-α in the ischemic cortex." (PMID 36160711, 2022). "Targeting P2X4 receptors improves postcentral stroke pain through the TNF-α/TNFR1/GABAAR pathway." (PMID 35265224, 2022). "These emerging studies provide new research ideas for anti-TNF-α treatment of stroke." (PMID 35265224, 2022). "In this context, potentially less toxic thalidomide/pomalidomide analogs with the ability to lower TNF-α and dampen the immune response both systemically and within the central nervous system may hold potential as a treatment strategy for stroke." (PMID 35631536, 2022). "dBET1 markedly reduced inflammation and oxidative stress after stroke, indicated by multiple pro-inflammatory cytokines and chemokines including IL-1β, IL-6, TNF-α, CCL2, CXCL1 and CXCL10, and oxidative damage markers 4-hydroxynonenal (4-HNE) and gp91phox and antioxidative proteins SOD2 and GPx1." (PMID 35761277, 2022). "In patients with stroke, blood samples were taken between the 3rd and 7th day after stroke-onset to avoid interactions within the acute phase, because it has already been shown that the expression of FAP is induced by macrophage-derived TNFα which is a mediator of post-stroke inflammation." (PMID 36568546, 2022). "We speculate that this is because of how TNF-α plays a role in stroke prognosis, which is complex and diverse, and these specific mechanisms need to be further investigated." (PMID 35265224, 2022). "Of them, Interleukin-1 beta (IL-1β) and tumor necrosis factor alpha (TNF-α) appear to play a particularly important role in stroke pathology, since they have a damaging effect on neuronal and glia cells and enhance the release of proinflammatory prostaglandins." (PMID 36358492, 2022). "In addition, plasma TNF-α levels were markedly elevated in stroke patients compared with healthy controls." (PMID 35781632, 2022). "In addition, increased plasma levels of TNF-α determined on admission also correlated with the volume and severity of the stroke and the functional outcome of the patient." (PMID 36142524, 2022). "Also, IL-1β, IFN-γ, and TNF-α showed greater percentage decrease when stroke monocytes were involved in both trans-well and contact co-cultures, as compared to when healthy control monocytes were involved." (PMID 36277912, 2022). "In mice, a decrease in neutrophils was demonstrated in various tissues, such as the lung, brain, and intestinal mucosa, in response to the inflammatory process, as well as a decrease in serum concentration of TNF-α, which occurs in ischemia–reperfusion injury and stroke." (PMID 35202287, 2022). "Therefore, it is a promising research direction to use TNF-α as a biomarker of stroke development process or prognosis." (PMID 35265224, 2022).
Stroke (continued). "However, after stroke or ex vivo stimulation, these cells dramatically increased their production of TNF, IFN-γ, and MCP-1/CCL2." (PMID 34711943, 2022). "Thus, the invasion and accumulation of TNF-α-activated platelets into the ischemic area of the cortex mediate the pathological progression of stroke." (PMID 35781632, 2022). "Therefore, in stroke, the TNF-α signal transduction is activated during ischemic injuries, and this fact has been further verified in subsequent clinical studies." (PMID 35370618, 2022). "The application value of the compound on stroke was assessed, and the results of ELISA assay suggested that the compound could obviously reduce the releasing of the TNF-α and IL-1β into the plasma in a dose-dependent manner." (PMID 35711621, 2022). "In addition, plasma TNF-α and IGF-1 levels were increased and decreased in stroke patients, respectively, and miR-424 levels in both lymphocytes and neutrophils were negatively correlated with plasma TNF-α, IL-10, or IGF-1 levels." (PMID 36275741, 2022). "Therefore, this article reviews the research progress of TNF-α and its antagonists and discusses its application prospect in the treatment of stroke." (PMID 35265224, 2022). "In addition, IL-1α, TNF and C1q can also differentiate astrocytes into the A1 phenotype, which is detrimental to stroke recovery." (PMID 35356292, 2022). "Moreover, HLA‐DR expression on monocytes from stroke patients was inversely correlated with the development of infections, and these “exhausted” monocytes of stroke patients also had a decreased capacity to release TNF‐α after stimulation." (PMID 35971650, 2022). "This may be related to the model used, as it has been suggested that pregnant stroke-prone spontaneously hypertensive rats show higher concentrations of TNF-α compared to normal SHR." (PMID 36355514, 2022). "Generally, cytokines such as TNF-α and IL-6 are upregulated in the brain after a stroke." (PMID 36076942, 2022). "Notably, strategies to reduce systemic inflammation including splenectomy to reduce myeloid cell mobilization and inhibition of pro-inflammatory cytokines interleukin-1β or tumor necrosis factor-α result in a smaller stroke size after MCAo in rodents." (PMID 36279013, 2022). "Some of the first data on how ABCs influence stroke outcomes show that the CD11bhigh subset can influence microglial phenotypes post-stroke to aid in phagocytosis, although the ABCs themselves can also secrete TNF-α which promotes prolonged neuroinflammation." (PMID 36446955, 2022). "Moreover, hypercholesterolemic mice show elevated ischemia‐induced plasma levels of TNFα and worsened outcome after stroke." (PMID 33369048, 2021). "Since NS19504 treatment promoted the outcome of stroke, we detected whether inflammation affects the significant difference between groups, and the mRNA levels of inflammation factors TNF-α, IL-1β, IL-6, IL-10, and TGF-β were examined." (PMID 34276309, 2021). "Similarly, higher levels of both TNF-α and IL-1β in the serum of stroke patients were found to correlated with poor stroke outcomes one year after stroke." (PMID 34884906, 2021). "It has been shown that IL-6 and TNF-α stimulate the synthesis and secretion of several chemotactic factors, which activate and attract peripheral blood leukocytes (neutrophils and monocytes) to the site of stroke lesions." (PMID 34433866, 2021). "Modulating this inflammatory response, particularly through tumor necrosis factor (TNF), interleukin (IL)-1, IL-6, and IL-10, may be the next frontier in stroke recovery." (PMID 34393973, 2021). "TNFα is also a well-known mediator of vascular dysfunction, and its up-regulation under inflammatory conditions as well as in the plasma of ischemic stroke patients has been shown repeatedly and even correlates with stroke damage and lesion size." (PMID 34571963, 2021).